MTOR (mechanistic target of rapamycin kinase)
Diseases named in the same sentence as MTOR in open-access papers (continued):
Sharing a sentence is not in itself a finding about the gene and the disease.
Huntington disease (47 papers, 2010 to 2025). Huntington disease (HD) is a rare neurodegenerative disorder of the central nervous system characterized by unwanted choreatic movements, behavioral and psychiatric disturbances and dementia. "This includes specific signaling pathways related to mTOR itself, as well as those implicated in Huntington’s disease and the elF4 and p70S6K pathways." (PMID 38927348, 2024). "Another example is a study on Huntington disease (HD), in which a decrease in mTOR activation associated with sequestrated Huntingtin protein (Htt) aggregates in postmortem HD brains was found." (PMID 34215725, 2021). "For instance, a decrease in beclin-1 expression leads to accumulation of mutant huntingtin protein in Huntington’s disease (HD) and loss of laforin polyglucosan inclusions in Lafora’s body disease via activation of mTOR (mammalian/mechanistic target of rapamycin) signaling pathway." (PMID 30866990, 2019). "It has also been proposed that blockade of striatal mTOR signalling caused by the sequestration of Rhes by mutant Huntingtin might underlie the pronounced atrophy of the striatum in Huntington disease." (PMID 23027611, 2012). "Since mHTT is SUMOylated at multiple sites and enhances perinuclear association of mTOR in Huntington disease cells, we speculate that SUMOylation of mHTT may further facilitate mTOR signaling and affect disease progression in cooperation with SUMOylation of GβL in HD conditions." (PMID 38395307, 2024). "We have previously demonstrated that the striatal-enriched small G protein Rhes that harbors N-terminal SUMO-E3-like domain that SUMOylates mutant huntingtin (mHTT) and directly binds and activates mTOR to promote Huntington's disease pathogenesis." (PMID 38395307, 2024). "In a fly model for Huntington's disease (HD), treatment with the mTOR inhibitor rapamycin in conjunction with lithium is more protective than treatment with either drug alone." (PMID 37746513, 2023). "Restoring mTOR activity by overexpression of constitutively active Rheb showed beneficial effect not only in muscle, but also in neurological disorders, such as Huntington's disease." (PMID 28130275, 2017). "Restoring the normal homeostasis in Huntington's disease seems possible; one such plan is to up-regulate the innate autophagy process by inhibiting MTOR activity within the cell." (PMID 27924190, 2016). "The protective effects of rapamycin mediated by the induction of autophagy were demonstrated in mouse models of Huntington's disease, in which inhibition of mTOR promoted the degradation of protein aggregates via autophagy." (PMID 27047390, 2016). "For example, activation of autophagy by the mTOR (mammalian target of rapamycin) inhibitor rapamycin attenuates the accumulation of mutant huntingtin and is neuroprotective in a Drosophila model of Huntington’s disease." (PMID 22392734, 2012). "For example, a study reporting down-regulation of mTOR signaling in huntingtin-accumulating neurons in a mouse model of Huntington's disease at the same time showed that treating the mice with rapamycin was protective." (PMID 20862226, 2010). "In addition to autophagy upregulators acting on the mTOR pathway, also mTOR-independent autophagy upregulators have been widely studied, mainly in Huntington’s disease." (PMID 31344897, 2019). "mTOR activity is modified in various pathologic states of the nervous system, including brain tumors, tuberous sclerosis, cortical displasia and neurodegenerative disorders such as PD, AD, and Huntington's disease (HD)." (PMID 26046303, 2015). "Furthermore, it has been observed that mTOR gets sequestered in polyglutamine aggregates during Huntington’s disease, resulting in decreased mTOR-dependent TOP translation and introduction of autophagy, thereby serving a protective function." (PMID 24045637, 2013).
Huntington disease (continued). "The mTOR pathway in humans is an important contributor to disease in various cancers, including hematologic malignancies and neurodegenerative diseases, such as Huntington disease, via still unclear mechanisms of suppression of autophagy and myopathies." (PMID 22540037, 2012). "Indeed, the therapeutic scope for upregulation of autophagy by mTOR inhibitors extends beyond Huntington's disease, as CCI-779 treatment also demonstrated protective effects in a mouse model of spinocerebellar type 3." (PMID 21087849, 2011). "Ubiquitin mediated proteolysis (p < 0.01), Neurotrophin signaling (p < 0.01), mTOR signaling (p < 0.01), AMPK signaling (p < 0.01), FoxO signaling (p < 0.01) and Huntington’s Disease pathway (p < 0.01) were also enriched in our analysis." (PMID 29707120, 2018). "Increasing evidence reveals that mTOR could be activated or inhibited depending on the pathologic status of the nervous system, e.g. brain tumors, tuberous sclerosis, cortical dysplasia and neurodegenerative diseases such as PD, Alzheimer's disease (AD), and Huntington's disease (HD)." (PMID 26859572, 2016). "Further to this it has been demonstrated that genetic inhibition of mTOR, by overexpression of TSC1 and TSC2, conferred neuroprotective effects in a Drosophila model of Huntington's disease." (PMID 21087849, 2011). "We initially demonstrated that upregulation of autophagy, using the mTOR inhibitor rapamycin or its water-soluble ester CCI-779, reduced levels of soluble and aggregated mutant huntingtin and was protective in cell, Drosophila and mouse models of Huntington's disease." (PMID 21087849, 2011).
Ewing sarcoma (46 papers, 2010 to 2026). A small round cell tumor that lacks morphologic, immunohistochemical, and electron microscopic evidence of neuroectodermal differentiation. "mTOR inhibitor causes inhibition of Ewing’s sarcoma cells in vitro, suggesting a possible therapeutic role in ESFT." (PMID 20924476, 2010). "Similarly, preclinical data on Ewing sarcoma indicate the ability of combinatorial approaches with anti-IGF1R to promote antitumor activity when associated with mTOR inhibitors or chemotherapy (trabectedin)." (PMID 40909947, 2025). "The mTOR inhibitor ridaforolimus was first evaluated in Ewing sarcoma patients in a phase I trial against advanced solid tumors, which reported 4 partial responses in 32 evaluable patients." (PMID 35409176, 2022). "In Ewing sarcoma, we previously documented that the inhibition of the mTOR/AKT/PI3K pathway sets in motion an hnRNPM-dependent alternative splicing program that limits the therapeutic efficacy of these pharmacologic inhibitors." (PMID 32023846, 2020). "Significantly, Ewing sarcoma cells were highly sensitive to PI3Kα and mTOR inhibition with IC50 values in the nanomolar range for the combination of both inhibitors." (PMID 31492956, 2019). "Ganitumab (currently in a metastatic Ewing sarcoma clinical trial) and mammalian target of rapamycin (mTOR) inhibitors (currently in a trial proposal) are also included using the task force’s work flow for comparison." (PMID 31031965, 2019). "Responses to anti-IGF-1R therapy alone or in combination with mTOR inhibition in Ewing sarcoma patients have been reported, as have responses to Apo2L/TRAIL therapy in chondrosarcoma patients." (PMID 27486883, 2016). "The application of these tools has previously revealed means of response and resistance in two cases of refractory Ewing sarcoma that responded to combination therapy with insulin-like growth factor 1 receptor and mTOR inhibition." (PMID 26444865, 2015). "The recent study in combination with mammalian target of rapamycin (mTOR) inhibitor temsirolimus in the relapsed/refractory setting (NCT00880282) also demonstrated best single-agent activity in Ewing sarcoma tumors." (PMID 23755370, 2013). "Inhibition of IGF1R and/or IGF1R and mTOR has resulted in significant clinical activity in patients with Ewing's sarcoma." (PMID 21494688, 2011). "This pilot study assessed two patients with advanced Ewing's sarcoma treated with IGF1R antibody alone followed by combined IGF1R inhibitor plus mammalian target of rapamycin (mTOR) inhibitor treatment once resistance to single-agent IGF1R inhibitor developed." (PMID 21494688, 2011). "Treatment of Ewing sarcoma cells with a dual inhibitor (BEZ235) of PI3K and the mechanistic target of rapamycin (mTOR), a downstream kinase in the pathway, caused extensive reprogramming of the cellular transcriptome, with thousands of genes modulated at either expression or splicing level." (PMID 34680108, 2021). "Moreover, hnRNPM guides an AS program involving multiple pre-mRNAs to confer resistance of Ewing sarcoma cells to inhibition of the PI3K/AKT/mTOR signal pathway." (PMID 34145290, 2021). "A former study has shown that E2F6 could regulate both AKT/mTOR and Wnt/β-catenin pathways in Ewing’s sarcoma." (PMID 31682716, 2020). "Importantly, in TC71 and RDES Ewing sarcoma cells, combined PI3Kα and mTOR inhibition resulted in reduced nuclear GLI1." (PMID 31492956, 2019). "Anti-IGF1R therapies have exhibited promising preclinical activities in Ewing sarcoma models, but appear to be inadequate to induce sustained clinical response either as monotherapy or in combination with mTOR inhibitors, in part due to toxicity of blocking IGF1R signaling in normal tissues." (PMID 27259270, 2016). "Ewing’s sarcoma had upregulated p-Akt and p-mTOR, predominantly mTORC2." (PMID 23922674, 2013). "Moreover, ezrin promotes growth and survival via AKT/mTOR pathway activation in Ewing's sarcoma cell lines." (PMID 19680458, 2010).
Ewing sarcoma (continued). "Importantly, it has been proved that E2F6 could regulate both AKT/mTOR and Wnt/β-catenin pathways in Ewing’s sarcoma." (PMID 31682716, 2020). "E2F6 could regulate AKT/mTOR and Wnt/β-catenin pathways in Ewing’s sarcoma." (PMID 31682716, 2020). "Also, combination of IGF-1R and mTOR inhibition showed clinical benefits in Ewing's sarcoma." (PMID 23663564, 2013). "In Ewing sarcoma, ATF3 positively mediates PI3K/AKT/mTOR signaling, which was identified as differentially enriched between and Ptf1acreERT/+KRASG12D/+ and APK organoids." (PMID 41198649, 2025). "In Ewing sarcomas, hnRNPM-dependent AS promoted drug resistance and drove resistance to the inhibition of the PI3K/AKT/mTOR pathway." (PMID 34294833, 2021). "We identified the HH effector GLI1 as a target for dual PI3Kα and mTOR inhibition in SHH-type medulloblastoma and confirmed these results in HH-driven Ewing sarcoma cells." (PMID 31492956, 2019). "We found dual PI3Kα and mTOR inhibition strongly reduced the amount of nuclear GLI1 protein in HH-driven medulloblastoma and similar results were observed in Ewing sarcoma, another HH-driven paediatric cancer." (PMID 31492956, 2019). "In a small study that sequenced the tumors of a few patients, it was intriguing that PTPRD germline aberrations conferred clinical benefit to patients with Ewing sarcoma who received therapy directed at the IGF1R and mTOR pathway." (PMID 26510912, 2015). "Ewing sarcoma, for example, was sensitive to aurora kinases and to TORIN-2 (an mTOR inhibitor)." (PMID 42165630, 2026). "For instance, Ewing sarcoma and medulloblastoma cells were more sensitive to PKI-179, a phosphoinositide-3-kinase/mammalian target of rapamycin (PI3K/mTOR) inhibitor, while rhabdomyosarcoma cells were more sensitive to cobimetinib, a mitogen-activated protein kinase (MEK) inhibitor." (PMID 39240541, 2024). "In Ewing sarcoma cell lines and patient-derived xenograft (PDX) lines, AKT pathway activation protects Ewing sarcoma cells against BRD4 inhibitors, and IGF1R inhibitors and mTOR inhibitors suppress AKT pathway activation and synergistically enhance cancer cell sensitivity to BRD4 inhibitors." (PMID 38135679, 2023). "It is also plausible that single-agent IGF-1R-directed monoclonal antibodies and small molecule inhibitors are not effective enough to fully abrogate downstream mTOR signaling, as demonstrated in Ewing sarcoma preclinical models." (PMID 35284040, 2022). "Activation of mTOR, ERK and NF-kB was found in Ewing sarcoma tumor cell lines." (PMID 22577336, 2012). "Morphoproteomic analysis revealed that the mTOR pathway was activated in these two patients with advanced Ewing's sarcoma who showed response to combined IGF1R and mTOR inhibition, and the ERK pathway in the patient in whom resistance to this combination emerged." (PMID 21494688, 2011). "PI3K/Akt/mTOR signaling was shown to regulate HIF-1α activation by hypoxia, as well as HIF1α-mediated resistance to hypoxia-induced apoptosis, in various human adult and pediatric cancers, including rhabdomyosarcoma and Ewing’s sarcomas, nasopharyngeal, colorectal, and glioma tumors." (PMID 34199959, 2021). "Three Ewing sarcoma patients had responses to anti-IGF-1R therapy with or without mTOR inhibition." (PMID 27486883, 2016). "Although there are a number of studies relating the activation of PI3K/AKT/mTOR pathway with the activation of HIF-1α, and melatonin regulates the PI3K/AKT/mTOR pathway in several models, our results show that these events are not connected in Ewing sarcoma cells." (PMID 26252771, 2015).
Focal cortical dysplasia (46 papers, 2014 to 2025). A type of malformation of cortical development that primarily affects areas of neocortex. "In the brain, instead, somatic mutations altering the PI3K (phosphoinositide 3-kinase)-mTOR (mammalian target of rapamycin) pathway have been recognized as drivers of malformation, particularly in focal cortical dysplasia (FCD)." (PMID 41359183, 2025). "PIK3CA mutations affecting the mTOR–MAPK gene network cluster have been associated with focal cortical dysplasia and DRE and other epileptogenic brain lesions." (PMID 40103938, 2025). "Some patients with cortical malformations, such as hemimegalencephaly and focal cortical dysplasia, have been shown to carry mutations in mTOR." (PMID 37770184, 2023). "It is thought that hyperactivation of the mechanistic target of rapamycin (mTOR) pathway is a hallmark of malformation of cortical development such as focal cortical dysplasia or hemimegalencephaly." (PMID 37493877, 2023). "Emerging evidence reveals that mutations within genes involved in the mTOR pathway cause several brain abnormalities, including focal cortical dysplasia (FCD)." (PMID 36685832, 2022). "Tuberous sclerosis complex (TSC) and some focal cortical dysplasias (FCDs) are associated with dysfunctional mTOR signaling, resulting in increased cell growth and ribosomal S6 protein phosphorylation (phospho-S6)." (PMID 35587487, 2022). "De novo somatic variants in genes encoding components of the PI3K-AKT3-mTOR pathway, including MTOR, have been linked to hemimegalencephaly or focal cortical dysplasia." (PMID 34359351, 2021). "Recently, childhood intractable epilepsy with focal cortical dysplasia or low-grade tumor (e.g., ganglioglioma) has been reported as being caused by low-level somatic mutations in MTOR or BRAF3,29,30." (PMID 30837471, 2019). "For example, mTOR-pathway-activating somatic mutations cause two types of intractable epilepsy (hemimegalencephaly and focal cortical dysplasia) depending on the time of occurrence of the mutation and VAFs (10%–30% VAFs in hemimegalencephaly, and 1%–10% of VAFs in focal cortical dysplasia)." (PMID 36121845, 2022). "Focal cortical dysplasia (FCD) is one of the primary causes of refractory epilepsy in children, with disruptions in the mTOR pathway playing a significant role in the epileptogenesis of these disorders." (PMID 40358185, 2025). "Focal cortical dysplasia (FCD) is a major cause of refractory epilepsy and is associated with pathogenic variants in mTOR pathway genes, including DEPDC5, the most common cause of familial focal epilepsy." (PMID 40996830, 2025). "One patient diagnosed with Type II focal cortical dysplasia (FCD) had a somatic variant in RHEB, a gene that is known to play a major role in the mTOR signaling pathway and has been altered in patients with FCD13." (PMID 36631516, 2023). "Abnormal developmental features of the brain, including macrocephaly, focal cortical dysplasia, and GBM, have been shown to be associated with mTOR signalling pathways." (PMID 35096558, 2021). "Mutations in mTOR or the mTOR pathway have been found in hemimegalencephaly (HME) and focal cortical dysplasias (FCDs), both of which are highly correlated with medically refractory epilepsy." (PMID 33643212, 2021). "Inhibition of mTOR with rapamycin suppressed cytomegalic neurons and epileptic seizures, so identifying mTOR as a treatment target for intractable epilepsy in focal cortical dysplasia." (PMID 28082152, 2018). "Focal cortical dysplasias (FCDs) are localized MCDs, formerly believed to mostly result from a toxic insult to the developing brain, but recently also associated with DEPDC5 mutations and somatic mutations in MTOR, PIK3CA, AKT3, PTEN, TSC1 and TSC2." (PMID 35323703, 2022).
Focal cortical dysplasia (continued). "DEPDC5 (DEP Domain-Containing Protein 5) encodes an inhibitory component of the mammalian target of rapamycin (mTOR) pathway and is commonly implicated in sporadic and familial focal epilepsies, both non-lesional and in association with focal cortical dysplasia." (PMID 36067010, 2023). "In contrast, gain of mTOR activity in properly positioned mature neurons is sufficient to induce cortical hyperactivity, although abnormal placement of neurons is a key feature of TSC and focal cortical dysplasia." (PMID 36277492, 2022).